NF2 (NF2, moesin-ezrin-radixin like (MERLIN) tumor suppressor)
Diseases named in the same sentence as NF2 in open-access papers (continued):
Sharing a sentence is not in itself a finding about the gene and the disease.
meningioma (continued). "Moreover, the schwannoma/meningioma-derived NF2 LOF mutations not only inhibit its tumor suppressive function in the Hippo pathway, but also gain an oncogenic role for NF2 by activating the VANGL-JNK pathway." (PMID 39572544, 2024). "Another study found an enrichment of YAP1 fusions in pediatric NF2 wild-type meningiomas." (PMID 38571886, 2024). "The GSTM1 null genotype is a novel biomarker of 1p-22q-NF2- meningioma recurrence that resolves heterogeneity in existing meningioma subtypes and may be used to guide future clinical management decisions on extent of treatment to improve patient outcomes." (PMID 39726707, 2024). "Meningiomas not defined by NF2 mutations commonly have deletions in CDKN2A/B located on chromosome 9p, as well as TRAF7 mutations on chromosome 16p." (PMID 39796693, 2024). "Loss or functional inactivation of NF2 or other upstream Hippo Pathway mediators lead to deregulation and deinhibition of YAP1 and NF2 mutant meningiomas and/or cell lines express high levels of YAP activity and upregulate the expression of several canonical YAP1 targets (such as CTGF and CYR61)." (PMID 38571886, 2024). "All spinal meningiomas in this study were associated with NF2, but there was no significance noted in tumour locations between our sporadic and non-sporadic group." (PMID 39612013, 2024). "For example, we found very high RRs of low-grade gliomas following childhood meningioma (SIR = 43.2, 95% CI: 19.4, 96.1), which may suggest that a diagnosis of NF-2 might be implicated in increasing both the risk of childhood meningioma and subsequent glioma." (PMID 38243010, 2024). "Meningiomas, non-VS, and VS were found to be associated with NF2 in 2.3% (8/351) of the cases, and hemangioblastomas were associated with Von Hippel-Lindau syndrome in 44.4% (4/9)." (PMID 39229481, 2024). "Molecular markers such as NF2 mutations, copy number variations, and epigenetic modifications have further supported the fact that heterogeneity exists in meningioma behavior and that not every case should be treated with the same approach." (PMID 39618617, 2024). "Although there is expanded research on NF2-mutated meningiomas and schwannomas, there seems to be a lack of studies on NF2-mutated ependymomas." (PMID 39796693, 2024). "Among these genes, NF2 frameshift mutation (c.503delC:p.K170Rfs*43) in M1 and CREBBP frameshift mutation (c.3923delT:p.L1308Cfs*30) in M2 were highlighted upon comparison with previously published data on genes mutated in at least two cases of meningiomas." (PMID 39066986, 2024). "NF2 patients are likely to develop Schwannomas on the eighth cranial nerve that are followed by progressive deafness and spinal cord compression as well as meningiomas and peripheral nerve tumors." (PMID 39083549, 2024). "Discrepancy with our results may be explained by our study focusing on the differences between recurrent and primary 1p-22q-NF2- meningiomas." (PMID 39726707, 2024). "It is currently unknown if low- and high-grade NF2 mutant meningiomas equally rely on YAP1 signaling for their growth and/or survival and would be susceptible to targeted therapy against YAP1." (PMID 38571886, 2024). "Mann–Whitney U tests were utilized to assess the differences in the SWI features of meningiomas with and without S100 protein expression or NF-2 copy number loss." (PMID 38611661, 2024). "Although a recent study on sporadic NF2-altered meningioma showed that transcriptomic changes, multiple CNVs, hypermethylated status, and immune cell infiltration clearly affect clinical tumour behaviour, meningiomas in patients with NF2 have been scarcely evaluated." (PMID 37752594, 2023). "Indeed, missense mutations in TRAF7, KLF4, and AKT1 exist in 30%, 14%, and 12% of non-NF2 meningiomas, respectively." (PMID 38001599, 2023). "We next compared mRNA expression profiles of NF2 meningioma subgroups." (PMID 36937440, 2023).
meningioma (continued). "By corroborating these findings with the latest data and our results, we speculate that higher immune activity, including rich macrophages and NK T-cell activity, may contribute to the less aggressive tumour behaviour of meningiomas in NF2 patients." (PMID 37752594, 2023). "In addition, supratentorial ependymomas most commonly harbored the C11orf95 – RELA fusion (71% of tumors, also known as ZFTA-RELA) and meningiomas most frequently harbored fusions in NF2 and YAP1 (both 15% of tumors)." (PMID 36711972, 2023). "Alterations of NF-2 in chromosome 22 do not seem to play an important role in the onset of canine meningiomas, as opposed to human meningiomas, where they have been reported to predispose to the development of the tumors." (PMID 38137885, 2023). "Within the group of aggressive meningiomas lacking NF2 mutation, in approximately 5% of tumors alterations in chromatin regulators BAP1 and PBRM1 were encountered and correlate with a more aggressive clinical behavior." (PMID 36641486, 2023). "Finally, meningiomas were distinguished based on NF2 status and chromosomal instability (CIN) as “NF2-intact”, “NF2-deficient, low CIN (one or two chromosomal deletions)”, and “NF2-deficient, high CIN (more than two chromosomal deletions)”." (PMID 37296907, 2023). "Taken together with the high expression of BCL2 and GLI1, these results suggest that activation of Sonic Hedgehog pathway may contribute to NF2 meningioma development." (PMID 36937440, 2023). "While previous reports have performed clinical and histological analyses of meningiomas in NF2 patients compared with those of sporadic meningiomas, our study uniquely focused on the comparison of NF2 patients’ meningiomas with sporadic NF2-altered meningiomas." (PMID 37752594, 2023). "Moreover, NF2 meningiomas were subdivided into two distinct groups based on additional loss of chr1p." (PMID 36937440, 2023). "Meningiomas in the first group are devoid of NF2 alterations and chromosomal instability; may feature AKT1, TRAF7, or KLF4 mutations; have the best prognosis; and are expected to respond to cytotoxic drugs." (PMID 37296907, 2023). "Although some researchers report a more aggressive nature of meningioma in patients with NF2 mutation, in this case we did not observe tumor progression." (PMID 38001695, 2023). "However, the question remains as to why meningiomas in NF2 patients show less aggressive behaviour than sporadic meningiomas, despite the development of multiple NF2-altered meningiomas." (PMID 37752594, 2023). "Similarly, constitutive activation of YAP1 or the presence of YAP1-MAML2, a fusion protein that was identified in several meningioma patients, can drive the formation of tumors that resemble NF2 mutant meningiomas." (PMID 38001599, 2023). "A study involving the analysis of 57 meningiomas demonstrated a significant elevation of expression of these Hippo pathway-associated genes, in tumors involving NF2 mutations, but without any correlation with the grade of the meningioma." (PMID 38001599, 2023). "Activation of MEF2C promotes the expression of NF2 and E-cadherin in meningiomas and causes ferroptosis in tumor cells.MEF2C may be a potential therapeutic target for ferroptosis in meningiomas." (PMID 36910646, 2023). "Among the non-NF2-mutated group, the most common oncogene in WHO grade I meningiomas is TNF receptor-activated factor 7 (TRAF7), located on chromosome 16p13 (mutated in nearly 25% of all meningiomas), followed by the mutation in codon K409Q of KLF4 (encountered in about 15% of benign meningiomas)." (PMID 37760490, 2023). "Among the various driver gene mutations in meningiomas, NF2 alteration is the most commonly-found genetic abnormality in meningiomas, and only sporadic NF2-altered meningiomas may present benign, atypical, and malignant tumours." (PMID 37752594, 2023).
meningioma (continued). "Benign type B meningiomas with NF2 loss but no other chromosomal abnormalities have less PRC2 complex repressor activity compared to more aggressive type C meningiomas that lack both chr22q and chr1q." (PMID 36937440, 2023). "Our study was designed to reveal the clinical and molecular characteristics of meningiomas in NF2 patients, but not the immune mechanisms underlying meningioma behaviour." (PMID 37752594, 2023). "In addition, also mutations of the gene encoding for the PI3K catalytic subunit alpha (PIK3CA) have been found in about 7% of non-NF2-altered meningiomas." (PMID 36181606, 2023). "Whether meningiomas in NF2 patients are histologically more malignant than sporadic meningiomas remains controversial." (PMID 37752594, 2023). "Alterations in NF2 remain the most common genetic abnormality in meningiomas, found in up to 60% of sporadic cases, and its inactivation has been hypothesized to be an early tumorigenic event." (PMID 36840836, 2023). "Although patients with multiple meningiomas tend to require multiple interventions and exhibit a shorter overall PFR, NF2-associated IVMs could be controlled with SRS." (PMID 36769714, 2023). "However, only a few studies on meningiomas in patients with NF2 have focused on their clinical and histological characteristics." (PMID 37752594, 2023). "Notably, all the tumors in patients who had NF2 or multiple meningiomas were under good control after SRS." (PMID 36769714, 2023). "It has been proposed that separation into NF2 and non-NF2 meningioma could be a reasonable adjustment to the WHO classification." (PMID 37860270, 2023). "A study of 31 meningioma cases, using exome, epigenome, and RNA-seq analyses, revealed the presence of NF2 rearrangements in radiation-induced meningiomas, and this may be utilized to differentiate this type of meningioma from sporadic ones." (PMID 38001599, 2023). "NF2, also called NF2-schwannomatosis, is a completely penetrant autosomal dominant condition characterized by the development of bilateral vestibular schwannomas and also ependymomas and meningiomas." (PMID 38139220, 2023). "However, the question remains as to why meningiomas in NF2 patients show less aggressive behaviour than sporadic NF2-altered meningiomas, despite the development of multiple NF2-altered meningiomas." (PMID 37752594, 2023). "Deletions of NF2 seem to be a common characteristic condition of meningiomas." (PMID 38137885, 2023). "Taking this latest knowledge into consideration, we hypothesize that molecular mechanisms present in NF2 patients to maintain meningiomas at a benign phenotype." (PMID 37752594, 2023). "A nuclear localization sequence (NLS)-2SA-YAP1 lesion—which constitutively activated YAP1 to inactivate Nf2—was explored to determine whether it would suffice to produce meningioma-like tumors." (PMID 37898750, 2023). "Five of these NF2 meningiomas (N2, N4, N5, N9, and N10) had additional cytogenetic changes, including loss of the short arm of chromosome 1 (chr1p), while the other five (N1, N3, N6, N7, and N8) displayed no significant chromosomal instability aside from chr22q monosomy." (PMID 36937440, 2023). "Hence, our findings suggest that sporadic NF2-altered grade I meningioma mainly comprises immune-rich tumours, although some tumours are immune-poor." (PMID 37752594, 2023). "Meningiomas are the second most frequent type of tumours in NF2." (PMID 37752594, 2023). "Furthermore, of the four DREAM complex target genes shown to be upregulated in type C tumors, only PBK was higher in our NF2-2 meningiomas, while the expression of the 3 other genes (TTK, MELK, and CDK1) was not significantly different between the subgroups." (PMID 36937440, 2023). "Meningiomas occur with greater frequency in patients with germline mutations of genes such as type-2 neurofibromatosis (NF2), type-1 neurofibromatosis (NF1, 19–24% of adolescent meningiomas), type-1 multiple endocrine neoplasia (MEN1), SMARCB1, LZTR1, or SMARCE1 genes." (PMID 37760490, 2023).
meningioma (continued). "MC ben-1 meningiomas were enriched in NF2 mutations while the MC ben-2 subgroup was enriched in non-NF2 mutations including TRAF7, AKT1, KLF4, and SMO." (PMID 36840836, 2023). "Furthermore, several disease-causing mutations, including NF2, TRAF7, KLF4, AKT1 and SMO, have been described in meningiomas and compounds specific for driver mutations are currently under investigation in clinical trials." (PMID 38102708, 2023). "In contrast, NF2-mutant meningiomas show strong female gender predominance, arise with a wider anatomic distribution, although most frequently in the thoracic spine dorsally to the spinal cord, and can be calcified while displaying variable histologic subtypes (online resource)." (PMID 35943573, 2022). "Furthermore, NF2 is a commonly defective gene in meningioma and is understood to be a negative regulator of mTOR, therefore NF2 deletion will drive meningioma proliferation." (PMID 35216092, 2022). "Meningiomas with mutant NF2 are more likely to be atypical than meningioma of the TRAKLS group." (PMID 35213082, 2022). "Approximately 40% of sporadic meningiomas are independent of NF2 inactivation and are linked to other mutations discovered in high-throughput sequencing studies of large cohorts of meningiomas." (PMID 36713513, 2022). "Therefore, we analyzed the distribution of 5 somatostatin receptors (SSTR1, SSTR2A, SSTR3, SSTR4, SSTR5) in a large meningioma cohort including patients suffering from NF2 and higher grade meningiomas." (PMID 33899156, 2022). "Finally, YAP–MAML2 fusion is also observed in a subset of sporadic NF2 wildtype meningioma, whose methylomes mirror NF2 mutant tumours, and has also been reported in nasopharyngeal carcinoma." (PMID 35119068, 2022). "Notably, NF2-mutant meningiomas had a near-complete female predominance (n = 30/32, 94%) when compared to the balanced female–male incidence of AKT1-mutant tumors (n = 7/15, p = 0.0006)." (PMID 35943573, 2022). "Interestingly, specific polymorphisms affecting genes such as caspase 8, NF2, XRCC1, and BRIP1 are related to increased risk for meningioma rise." (PMID 35891812, 2022). "The chordoid meningiomas showed lower rates of mutation than non-chordoid high grade meningiomas, with infrequent NF2 and TERT promoter mutations." (PMID 35440040, 2022). "Although we posit that supratentorial NF2 meningiomas might have such an aggressive feature as copy number alteration in addition to Ki-67 and FOXM1, it was beyond the scope of this study." (PMID 35570314, 2022). "NF2, located on chromosome 22q, is the most commonly altered gene in meningioma." (PMID 36497370, 2022). "Unlike NF2-mutated meningiomas, SMARCB1/NF2 co-mutations localize anterior to the coronal suture and medially along the falx." (PMID 34846640, 2022). "applied copy number variation analysis, somatic point mutations, methylation profiles, and messenger RNA abundance to 121 meningioma patient samples to create four molecular groups of meningiomas: immunogenic, benign NF2 wild-type, hypermetabolic, and proliferative." (PMID 36686824, 2022). "Five IVMs were included in another study performing whole-genome sequencing of 775 meningiomas; two cases had NF2 mutation, one featured SMO mutation and no other mutations were found." (PMID 35049691, 2022). "Furthermore, it has been determined that inhibition of NF2 and E-Cadherin can promote ferroptosis-related cytotoxicity and lipid peroxidation in meningioma cell lines." (PMID 35530363, 2022). "Additionally, mutations that occur in the SMARCB1 gene, which were investigated in our patient, are reported as part of the genetic profile of non-NF2 meningioma." (PMID 35163107, 2022). "Unlike sporadic meningiomas that commonly harbor NF2 mutations, the same mutations are not seen in radiation-induced meningiomas." (PMID 36686824, 2022).
meningioma (continued). "By integrating driver gene mutation and tumour location, the “Supratentorial NF2” subgroup as well as the EOR and Ki-67 index, were identified as a significant predictor of recurrence of WHO grade I meningioma, clinically similar to the poor prognosis of WHO grade II/III." (PMID 35570314, 2022). "In a first step, the drugs were assessed on 3 human meningioma cell lines, 2 with NF2 deficiency (Ben-Men-1, CH-157MN) and one without (IOMM-Lee)." (PMID 36139608, 2022). "Other recurrent canonical somatic mutations are present in ∼40% of sporadic meningiomas and are not defined by NF2 inactivation." (PMID 35996584, 2022). "In addition to NF2 inactivation, loss of CDKN2A/B contributes to meningioma progression and has been associated with shorter time to recurrence in mice." (PMID 36686824, 2022). "These advances on NF2-related meningiomas represent a major step forward in therapeutics." (PMID 35712491, 2022). "Meningiomas are often considered a mark of severity in NF2 disease and are employed as prognostic features for genomic counseling; this inconsistent presentation of disease severity within one family epitomizes the challenge of defining the effect and function of such missense variants." (PMID 35332608, 2022). "A frequent aberration that can co-occur with TRAF7 is KLF4 mutations in up to 50% of NF2-nonmutated meningiomas of grade 1." (PMID 35565385, 2022). "NF2 gene inactivation is considered to play a significant role in the development of meningiomas." (PMID 36267986, 2022). "Furthermore, regarding WHO grade I meningiomas, the PFS of the group with the Hedgehog and the tumour necrosis factor-receptor associated factor 7 (TRAF 7) were shorter than that of the NF2 group." (PMID 35570314, 2022). "NF2 mutant meningiomas account for approximately 60% of all meningiomas." (PMID 36010600, 2022). "TERT promoter mutations also occur mostly (although not exclusively) in NF2-altered meningioma and, although uncommon, are highly associated with grade and decreased time to recurrence/progression." (PMID 36230612, 2022). "The expression scores of SSTR1, 2A, and 5 were significantly lower in meningiomas of NF2 patients." (PMID 33899156, 2022). "Further investigation of NF2 mutations in meningiomas has also revealed that these mutations are generally associated with convexity meningiomas rather than meningiomas of the anterior skull base." (PMID 35402234, 2022). "In contrast, meningiomas harboring an AKT1 mutation were predominantly located in the cervical spine (73.3%) and 87% of AKT1-mutant meningiomas (n = 13) (compared to 43.75% of NF2-mutant meningiomas, n = 14) arose ventrally or ventro-laterally to the spinal cord (p = 0.010)." (PMID 35943573, 2022). "First, the prevalence of NF2 mutations in grade 2/3 meningiomas was not as frequent as reported in some previous literature." (PMID 35774130, 2022). "The presence of NF2 alteration was found to have a significantly worse prognostic impact in supratentorial meningiomas, while it has a tendency to have a better prognostic effect in infratentorial meningiomas." (PMID 35570314, 2022). "Thus, prediction of the NF2 status before surgery can aid in the development of personalized treatment strategies for meningioma patients." (PMID 36267986, 2022). "The knowledge of NF2 status might play a role in decision making of appropriate clinical treatment strategies for meningioma patients." (PMID 36267986, 2022). "A second group of “Immune-enriched” meningiomas was distinguished by inactivation of NF2 without concurrent 1p loss, intermediate outcomes, and marked immune infiltrate." (PMID 36315366, 2022). "Patients with multiple meningiomas and NF2 were excluded, as well as previously irradiated lesions." (PMID 36011041, 2022). "Over half of sporadic meningiomas harbor somatic NF2-mutations and noninvasive clinical diagnostics can differentiate between NF2-mutated and non-mutated meningiomas, with important implications for patient care." (PMID 34846640, 2022).